CRP (C-reactive protein)
Diseases named in the same sentence as CRP in open-access papers (continued):
Sharing a sentence is not in itself a finding about the gene and the disease.
COVID-19 (continued). "Elevation of laboratory profiles of COVID-19 patients including C-Reactive Protein (CRP), interleukin-6 platelets, eosinophils, hemoglobin, and albumin also were described." (PMID 38039278, 2023). "In the study by colleagues from China, the CRP, PCT, and NLR were investigated in relation to their diagnostic and prognostic significance for COVID-19 mortality in groups related to the severity of the disease." (PMID 36983910, 2023). "Clinical manifestations (fever, chills, diarrhea, cough, etc.)and biological parameters (e.g., C-reactive protein (CRP) and CXCL10) in cohort 1 patients were strongly associated with severe COVID-19 and, in addition, with the occurrence of LC." (PMID 38139027, 2023). "We found that all forms of COVID-19 patients had increased monocyte counts and TT as well as increased serum levels of CRP, fibrinogen, and total anti-SARS-CoV-2 antibodies compared to the controls." (PMID 37373331, 2023). "For predicting the severe form of COVID-19, higher AUC values were achieved when CRP was analyzed together with the other inflammatory markers which also showed significant independent associations (Model1_1)." (PMID 37388734, 2023). "RDW has been associated with measures of inflammation, such as CRP, and was linked to the cytokine storm in these patients, highlighting RDW as a potential indicator for high-inflammatory risk in COVID-19." (PMID 36829793, 2023). "We identified a significant association between the increased value of ferritin (p < 0.0001, OR = 22.31), fibrinogen (p = 0.009, OR = 13.41), and C-reactive protein (p = 0.01, OR = 7.65), respectively, and the level of severity of COVID-19." (PMID 37623485, 2023). "Similar to our group with persisting symptoms only a minority of patients with post-COVID-19 sequelae show an elevation of CRP." (PMID 37416926, 2023). "Hospitalized COVID-19 patients (n = 48) demonstrated higher serum levels of 55 inflammatory proteins (p < 0.001), including hs-C-reactive protein levels (p < 0.05), compared to healthy controls (n = 48)." (PMID 37832397, 2023). "Serum levels of CRP, ferritin and D-dimer were measured in both groups and the results showed a highly significant increase of their mean levels in COVID-19 patients group compared to the healthy control group (P value = 0.0001*))." (PMID 36864077, 2023). "We can cite, as an example, the high levels of C-reactive protein, a protein whose expression is driven by IL-6, as also a biomarker of severe clinical manifestations of COVID-19." (PMID 37515295, 2023). "Laboratory values with the severe course of COVID-19 were characterized not only by a significant increase in serum CRP but also NLR compared with medium–severe COVID-19." (PMID 36975366, 2023). "As well, in a prospective study, PTX inhibits COVID-19 severity by reduction of IL-6 and c-reactive protein (CRP) and improved prognosis of patients when combined with antioxidants." (PMID 36850013, 2023). "The increase in the level of several biomarkers, including CRP, IL-6, as well as WBC counts, and D-dimer, has been associated with severe COVID-19." (PMID 37228441, 2023). "On the other hand, patients in cluster 1 were younger with fewer background diseases but worse COVID-19-related variables, such as high CRP, chest X-ray findings and O2 saturation." (PMID 37258639, 2023). "Patients who reattended ED, facilitated by the virtual ward service, had a higher mean CRP (53.63 vs 41.67 mg/L), presented to ED initially later in their COVID-19 illness (8 vs 6.5 days) and had a higher admission rate (61 vs 39%)." (PMID 37437035, 2023). "Our study results showed that CRP is a useful marker during COVID-19, both for illness severity assessment and disease prognosis, consistent with previous studies." (PMID 37790210, 2023).
COVID-19 (continued). "Increased levels of IL-6 and C-reactive protein (CRP) have been found in blood samples from COVID-19 patients with peak levels measured at 3 days after hospitalization in critically ill survivors and a continuous increase in non-survivors." (PMID 37168848, 2023). "The present study analyzed the therapeutic efficacy of NAC in reducing COVID-19 severity in terms of CRP, D-dimer, ferritin, PaO2/FiO2, duration of hospital and ICU stays, and mortality." (PMID 37534078, 2023). "For instance, patients with severe COVID-19 have higher CRP, D-dimer, and lactate dehydrogenase (LDH) levels but lower albumin levels than those with non-severe COVID-19." (PMID 37887751, 2023). "During two weeks of hospitalization, CRP levels in the plasma of patients with COVID-19 were significantly higher than in the plasma of volunteers in the control group and decreased from day 7 to 28 of observation." (PMID 37034572, 2023). "C-reactive protein (CRP), interleukin-6 (IL-6), neopterin, Kyn, Phe concentrations were significantly increased, and Trp levels depleted during acute COVID-19." (PMID 37038445, 2023). "We observed that COVID-19 patients with higher plasma suPAR levels had unfavorable CRP, LDH, and neutrophil profiles in the correlation analysis." (PMID 37108340, 2023). "Our study is the largest experience reporting the changes in PCT and CRP related to secondary bacterial infections acquired during the ICU stay of critically ill COVID-19 patients." (PMID 37887237, 2023). "The testosterone/LH ratio has also been linked to higher levels of C-reactive protein (CRP), whose rise is correlated with the severity of COVID-19." (PMID 36992094, 2023). "We previously conducted a pilot trial administering nasal Foralumab in subjects with mild to moderate COVID-19 and found a reduction in serum IL-6 and C-reactive protein and more rapid clearance of lung infiltrates in treated individuals." (PMID 36881624, 2023). "Altogether, these findings show that some parameters such as IL-6, IL-8, type I IFNs, CRP, neutrophil and platelet counts presented significant differences in patients with severe COVID-19 with different clinical outcomes (deceased versus discharged)." (PMID 36817433, 2023). "The adjustment factors included sex, age, body mass index (BMI), severity of COVID-19, C-reactive protein level, medical history, and therapeutic factors such as the use of remdesivir, steroids, or mechanical ventilation." (PMID 37968660, 2023). "We found a very strong correlation between the severity of the COVID-19 with the D-dimer and the C-reactive protein." (PMID 37390087, 2023). "The univariate Cox proportional hazards regression analysis showed that viral load, C-reactive protein (CRP), lactate dehydrogenase (LDH), and aspartate aminotransferase (AST) were significant risk factors associated with COVID-19 mortality." (PMID 36769445, 2023). "Increased D-dimer and CRP in severe COVID-19 and cerebrovascular events are constant findings with virus-associated microangiopathy." (PMID 38313184, 2023). "When levels of host proteins were compared between COVID-19 and TB patients, five (ApoA1, CRP, ferritin, SAA1/A2, and S100A12) showed promising discriminatory potential as all but ApoA1 were significantly higher in COVID-19 patients’ sera." (PMID 36590898, 2023). "This was also seen in a meta-analysis which showed elevated serum CRP, PCT, D-dimer, and ferritin among COVID-19 patients were associated with a poor outcome." (PMID 37887248, 2023). "It is believed that patients with increased levels of CRP in severe viral infections, such as COVID-19, are five times more likely to develop SARS." (PMID 39263681, 2023). "The quantifiable variables, including age and hs-CRP, Mb and hs-cTnI levels, were analyzed by ROC curve to obtain their optimal cut-off values, for evaluating the prognosis of COVID-19-infected patients with arrhythmia in the future." (PMID 37575983, 2023).
COVID-19 (continued). "CRP has been identified as a key biomarker whose levels increase significantly in patients with severe COVID-19 and determines the progression of the disease." (PMID 37810906, 2023). "X-ray abnormalities were one of the most frequent laboratory findings, followed by out-of-range WBCs and CRP in our study, which is similar to other published studies documenting changes in chest X-rays in patients with COVID-19." (PMID 37107008, 2023). "The elevated inflammatory markers including CRP, D-dimer, ferritin, and IL-6 in severe COVID-19 infected individuals support the inflammatory "cytokine storm" response theory." (PMID 38313184, 2023). "After Wilcoxon signed rank test, compared with the pre-COVID-19 phase, the COVID-19 phase had a significantly higher CRP (0.2 (0.1, 0.5) vs. 0.2 (0.1, 0.4) mg/dL, p = 0.001)." (PMID 36611127, 2023). "Its results underlined a statistically significant correlation between COVID-19 severity and the IL-6, IgG, neutrophil count, % neutrophils, NLR, PLR, CRP, AST, and urea." (PMID 36838284, 2023). "It is evident that CRP is a strong indicator of the inflammatory process and a predictor of COVID-19 disease severity." (PMID 36986336, 2023). "For example, there is some meta-analytic evidence from 4 trials that omega-3 fatty acid supplementation in COVID-19 patients led to a significant reduction in CRP levels." (PMID 37048015, 2023). "Patients in this second phase with severe COVID-19 often present with elevated D-dimer, C-reactive protein (CRP), IL-6, acute kidney injury, and heightened complement deposition." (PMID 37398192, 2023). "The laboratory findings of CBC, D-dimer and CRP provide an essential contribution to predicti COVID-19 severity and prognosis." (PMID 37545971, 2023). "At the same time, elevated D-dimer values correlate with inflammation markers such as CRP and IL-6, as in severe COVID-19." (PMID 37109161, 2023). "The present findings revealed a significant ability of anakinra to diminish several biomarkers such as ferritin, D-dimer, LDH, CRP and WBCs in COVID-19 patients in comparison to tocilizumab." (PMID 37046952, 2023). "Our results indicated that in COVID-19 patients, PCT and CRP values were associated with infections acquired during the ICU stay and can be used to support, together with clinical signs, rather than predict or rule out, the diagnosis of these infections." (PMID 37887237, 2023). "High levels of CRP were considered the most important predictor of COVID-19 severity in cancer patients." (PMID 37643201, 2023). "CRP and leukocyte counts were similar between the groups, but COVID-19 patients exhibited lower procalcitonin levels (p = 0.027)." (PMID 38137508, 2023). "There are several case reports with mixed results on reducing lung injury with CRP apheresis in patients with COVID-19-evoked respiratory distress syndrome." (PMID 37564640, 2023). "This large retrospective analysis in COVID-19 patients with an ICU stay > 11 days indicated that PCT and CRP values were associated with developing secondary infections." (PMID 37887237, 2023). "Some authors showed that the higher mortality rate in critically ill COVID-19 patients is due to older age, the impact of comorbidities, higher D-dimer values, higher CRP, use of invasive mechanical ventilation, vasopressors, and renal replacement therapy." (PMID 38034537, 2023). "In a small study from the first COVID-19 pandemic wave, CRP levels were elevated in the initial phase of illness and peaked on day 10 of illness." (PMID 37810906, 2023). "Very high values of C-reactive protein were more common in the group of patients with severe COVID-19 (p = 0.0001)." (PMID 37390087, 2023). "It seems that MDA and CRP levels in COVID-19 patients increased significantly, which is proportional to the severity of the disease." (PMID 38049886, 2023).
COVID-19 (continued). "For example, C-reactive protein (CRP), interleukin 6 (IL-6), and tumor necrosis factor alpha (TNFα) were significantly higher in patients with persistent symptoms after COVID-19 compared to patients that fully recovered." (PMID 37789266, 2023). "Nasal administration of a fully human anti-CD3 monoclonal antibody (Foralumab) reduced lung inflammation as well as serum IL-6 and C-reactive protein in moderate cases of COVID-19." (PMID 36881624, 2023). "Mortality due to COVID-19 has been correlated with laboratory markers of inflammation, such as C-reactive protein (CRP)." (PMID 36833680, 2023). "COVID-19 patients with elevated creatinine had a significantly higher median CRP, older age, and were symptomatic for a longer period than patients with normal creatinine." (PMID 36819137, 2023). "The study findings also suggest that clinicians should consider monitoring liver function in patients with COVID-19, especially in males, and those with elevated CRP levels." (PMID 37363445, 2023). "It is important to highlight that CRP is one of the inflammatory biomarkers used to evaluate COVID-19 severity." (PMID 37510958, 2023). "Comparing different groups of COVID-19 patients with a healthy control group, the levels of IL-6, serum ferritin, CRP, and ESR demonstrated significant differences." (PMID 37363608, 2023). "We constructed forest plots to estimate the summary effect of NAC on COVID-19 severity indices and mortality using data on CRP, D-dimer, ferritin, duration of hospital and ICU stay, PaO2/FiO2, and the number of deaths." (PMID 37534078, 2023). "In post-COVID-19 patients, we must give significance to complaints of low back pain because it can be due to intramuscular edema in multifidus and erector spinae, and it may be associated with raised c-reactive protein, erythrocyte sedimentation rate, creatinine kinase, and D-dimer levels." (PMID 38186417, 2023). "A meta-analysis including 16 studies revealed CRP levels were positively related to the severity of COVID-19 in all except one study." (PMID 37519620, 2023). "Severe COVID-19 is accompanied by increased MB, CRP, Tbil, Dbil, Neu counts and decreased LYM counts, PLT, and Cr clearance rate." (PMID 37223120, 2023). "Our evidence also stresses the key prognostic role played by NT-proBNP, eGFR, and CRP in older COVID-19 patients." (PMID 37760914, 2023). "By combining sPDL-1 levels with the number of peripheral lymphocytes and sPDL-1 levels with CRP levels, we highlighted the dynamic role of sPDL-1 in modulating the immune and inflammatory response during COVID-19." (PMID 37959277, 2023). "Among the patients with SP–SPM with COVID-19, the laboratory findings indicated a greater incidence of lymphopenia and increased levels of C-reactive protein, urea, and creatinine compared to the non-COVID-19 cases." (PMID 37888108, 2023). "In pre-intervention, a high concentration of CRP was observed in the experimental groups compared with reference values, corroborating a previous study that revealed a high concentration of CRP in patients after recovery from COVID-19." (PMID 37700761, 2023). "Thirdly, CRP was identified as a significant and independent predictor for infiltrate above the median in COVID-19 (p < 0.001), opposite to age, obesity, chronic pulmonary disease, chronic kidney disease, and severe course of disease (each p = n.s)." (PMID 37733154, 2023). "As for the routine laboratory data, as previously shown in many studies, we found gross changes in ALT, GGT, LDH, IL-6, ferritin, and CRP are a consequence of severe COVID-19 in aged men." (PMID 36831321, 2023). "A meta-analysis of nine observational trials reported a median reduction of 0.67 ng/dL and 10.6 mg/dL for PCT and CRP, respectively, after the administration of Tocilizumab in COVID-19 patients." (PMID 37887237, 2023).
COVID-19 (continued). "Elevated CRP values are also seen in patients with severe COVID-19 and a trend towards increased values within the mortality cohort was seen between days 1 and 10 of ICU admission, although the predictive value was not sustained." (PMID 37801184, 2023). "The CRP, a serum inflammatory marker protein, showed abnormal levels in children with COVID-19 and has been identified as a probable biomarker for disease severity." (PMID 37378147, 2023). "A statistically significant decrease in hs-CRP levels was observed between group-1 and 2 and also between group-1 and 3, indicating better responses of critical COVID-19 patients to their effective treatment." (PMID 37744945, 2023). "Regarding the percentage of pulmonary infiltrates in COVID-19, stepwise multiple linear regression analyses adjusted for the potential confounding variables were performed separately for each IL-6, CRP, and leucocytes." (PMID 37733154, 2023). "The results of numerous studies show that there is a direct correlation between the levels of CRP in patients with COVID-19 and their respective outcomes in terms of death and length of hospital stay." (PMID 36975366, 2023). "The deterioration model of COVID-19 was constructed with five indices, including C-reactive protein, neutrophil count/lymphocyte count (NLR), albumin/globulin ratio (A/G), international normalized ratio (INR), and blood urea nitrogen (BUN)." (PMID 37122321, 2023). "CRP levels were found to be significantly elevated in the initial phases of the infection in patients with severe COVID-19 also prior to indications of critical findings with CT." (PMID 37173883, 2023). "This also overlaps with our finding that elevated C-reactive protein values were more common in infants with COVID-19." (PMID 38257763, 2023). "This study population also showed that in terms of diagnostic performance on ROC analysis, CRB-65 was, overall, comparable to CRP for predicting inpatient mortality in COVID-19 patients." (PMID 37760863, 2023). "Previous meta-analysis study has also shown the remarkably higher serum CRP and D-dimer levels in COVID-19 diabetic patients." (PMID 36634951, 2023). "Seven publications (n = 132) reporting data of COVID-19 patients showed a significant reduction in serum CRP levels after treatment (MD = −45.02 [95%-CI: −82.64; −7.39] mg/dL, I2 = 95%, p = 0.026)." (PMID 38002070, 2023). "Age, neutrophil-to-lymphocyte ratio, D-dimer, and C-reactive protein were identified as major predictors of mortality for COVID-19 patients by LASSO regression." (PMID 37362565, 2023). "The C-reactive protein of the COVID-19 patients were higher than the upper limit of the normal reference value, as well as the erythrocyte sedimentation rate of the patients with liver injury." (PMID 36860673, 2023). "On the one hand, this study obtained results consistent with those of other studies by recognizing the features of C-reactive protein, the ratio of lymphocytes, lactic acid, and serum calcium as having a substantial impact on COVID-19 prognostic predictions." (PMID 36116079, 2023). "In the univariate analysis, age, BMI, lymphocytes, neutrophils, LDH, CRP, ferritin, D-dimer, albumin, AST, ALT, and creatinine were significantly associated with severe COVID-19." (PMID 36653462, 2023). "PIMS-TS patients exhibited higher systemic markers of inflammation when compared to acute COVID-19 patients, including leucocytosis (p = 0.01), neutrophilia and elevated CRP (p < 0.001)." (PMID 38027272, 2023). "Some studies reported that COVID-19 patients with poor prognosis had significantly elevated levels of D-dimers, CRP, LDH, and lymphocytopenia at admission to the hospital." (PMID 36900724, 2023). "The elevated inflammatory markers CRP, IL-6, and D-dimer in most of the COVID-19-infected individuals support the inflammatory "cytokine storm" response theory and hypercoagulation status in severe COVID-19-infected individuals." (PMID 38313184, 2023).